SNX10 (sorting nexin 10)
Description:
Probable phosphoinositide-binding protein involved in protein sorting and membrane trafficking in endosomes. Plays a role in cilium biogenesis through regulation of the transport and the localization of proteins to the cilium. Required for the localization to the cilium of V-ATPase subunit ATP6V1D and ATP6V0D1, and RAB8A. Involved in osteoclast differentiation and therefore bone resorption.
Synonyms: OPTB8
Tractability: Antibody: UniProt places it where antibodies can reach, with medium confidence. PROTAC: ubiquitination databases record sites on it; its protein half-life has been measured.
Gene: Protein-coding gene on chromosome 7 (26,291,862 to 26,374,383, forward strand). Ensembl gene ENSG00000086300.
Subcellular location: Cytoplasm; Endosome membrane; Cytoplasm, cytoskeleton, microtubule organizing center, centrosome
Subcellular location (Human Protein Atlas): Microtubules; Nucleoplasm; Cytosol; Nucleoli; Primary cilium
Gene Ontology:
Molecular function: 1-phosphatidylinositol binding; ATPase binding; protein binding; phosphatidylinositol phosphate binding; phosphatidylinositol binding
Biological process: cilium assembly; endosome organization; protein localization to centrosome; protein localization to cilium; osteoclast differentiation; vesicle organization; intracellular protein transport
Cellular component: centrosome; cytosol; endoplasmic reticulum; extrinsic component of endosome membrane; microtubule cytoskeleton; nucleus; endosome; apical cytoplasm; cytoplasm; endosome membrane; secretory granule
Genetic constraint (gnomAD): Loss-of-function variants: 12 observed, 12.74 expected, observed/expected ratio (o/e) 0.94, 90% interval 0.6 to 1.52. The synonymous counts are far from expectation, so gnomAD's model fits this gene poorly and the ratio says little. Missense variants: 95 observed, 132.37 expected, observed/expected ratio (o/e) 0.72, 90% interval 0.61 to 0.85. Synonymous variants: 27 observed, 44.43 expected, observed/expected ratio (o/e) 0.61, 90% interval 0.45 to 0.84.
Gene-disease validity (ClinGen):
ClinGen rates the evidence that SNX10 causes each of these diseases.
autosomal recessive osteopetrosis 8 (autosomal recessive): Definitive.
Homologues: Orthologues: chimpanzee SNX10 (100% identical), pig SNX10 (98% identical), guinea pig SNX10 (97% identical), macaque SNX10 (97% identical), mouse Snx10 (96% identical), dog SNX10 (93% identical), rat Snx10 (92% identical), tropical clawed frog snx10 (60% identical), zebrafish snx10a (55% identical), rabbit SNX10 (52% identical), zebrafish snx10b (46% identical). Paralogues in human: SNX11 (46% identical), SNX2 (24% identical), SNX1 (22% identical), SNX3 (21% identical), SNX30 (21% identical), SNX12 (20% identical), SNX18 (20% identical), SNX33 (19% identical), SNX4 (18% identical), SNX7 (18% identical), SNX8 (17% identical), SNX6 (16% identical), and 3 more.
Diseases named in the same sentence as SNX10 in open-access papers:
SNX10 is named in the same sentence as 68 diseases in open-access papers, as found by Europe PMC text mining. Sharing a sentence is not in itself a finding about the gene and the disease. The quoted sentences say what the papers report.
osteopetrosis (18 papers, 2015 to 2025). Osteopetrosis, also known as marble bone disease, is a descriptive term that refers to a group of rare, heritable disorders of the skeleton characterized by increased bone density on radiographs. "Here, we describe a 4-year-old boy with a large homozygous deletion in the 5′-untranslated region (5′-UTR) of SNX10 causing osteopetrosis autosomal recessive 8 with milder phenotypes." (PMID 36526684, 2023). "SNX10 is required for osteoclast differentiation and function and missense mutations cause osteopetrosis, a heritable disorder of osteoclasts, following altered endocytosis." (PMID 36795488, 2023). "In the original work, SNX10-dependent osteopetrosis was reported to show few and small osteoclasts, while in a more recent paper SNX10-deficient osteoclasts were larger and pale at tartrate-resistant acid phosphatase (TRAP) staining." (PMID 30837952, 2019). "Homozygote mutations in SNX10 gene, located on 7p15.2, causes autosomal recessive form of osteopetrosis." (PMID 29090071, 2017). "In conclusion, the Västerbotten intermediate form of osteopetrosis is caused by a splice site sequence variant in the SNX10 gene and differs in clinical characteristics from other intermediate types of ARO." (PMID 28592808, 2017). "In summary, we report a novel mutation of SNX10 gene in a female patient with osteopetrosis who died at the age of 17 years." (PMID 29090071, 2017). "Since osteoclasts activity highly depends on this cellular phenomenon, mutation in SNX10 gene can be easily assumed to cause osteoclast dysfunction and consequently osteopetrosis." (PMID 29090071, 2017). "Based on our own findings and reports on mice and humans with TCIRG1 mutations, we conclude that the Snx10 KD mice have a phenotype of osteopetrosis with super-imposed rickets: osteopetrorickets." (PMID 25811986, 2015). "Global Snx10-deficiency in mice results in a combined phenotype: osteopetrosis (due to osteoclast defect) and rickets (due to high stomach pH and low calcium availability, resulting in impaired bone mineralization)." (PMID 25811986, 2015). "In this study we report that global Snx10-deficient mice (Snx10 KD) die at 3 weeks post-partum and exhibit severe osteopetrosis with a superimposed mineralization defect." (PMID 25811986, 2015). "A group of nine SNX10 intermediate osteopetrosis patients was described in the Swedish county of Västerbotten, which were caused by a splice site mutation in the SNX10 gene that led to a frameshift and premature termination of translation of the protein product." (PMID 34095139, 2021). "Therefore, osteoclast-specific Snx10 deficiency resulted in osteopetrosis." (PMID 25811986, 2015). "A homozygous ~70 kb deletion chr7:g.(26249558_26251671)-(26321193_26322492) in SNX10 identified by 1 M array comparative genomic hybridization was previously reported with osteopetrosis." (PMID 36526684, 2023). "Analysis and reporting patients with mutation in this gene can be very helpful to obtain a better picture of the disease phenotype in SNX10-related osteopetrosis." (PMID 29090071, 2017). "Snx10 knock out mice have impaired gastric acidification and are severely hypocalcaemic compared to wild type littermates, resulting in rickets as well as osteopetrosis (osteopetrorickets)." (PMID 28592808, 2017). "The Snx10 KD mice thus exhibit a phenotype that is a combination of osteopetrosis (due to impaired osteoclast resorption) and rickets (impaired mineralization due to poor calcium absorption)." (PMID 25811986, 2015). "Put together, these results confirm a combined phenotype in Snx10 KD mice characterized by both a bone mineralization defect (rickets) and osteopetrosis due to defective osteoclast resorption." (PMID 25811986, 2015). "One example is the human osteopetrosis caused by SNX10 (sorting nexin 10) deficiency, where osteoclasts are nonresorbing." (PMID 38315213, 2024). "Intermediate forms of osteopetrosis are caused bydefects in the PLEKHM1 and SNX10 genes." (PMID 37465191, 2023).
osteopetrosis (continued). "In this study, we derived and expanded iPSC lines successfully from osteopetrosis patients with mutations in TCIRG1, CLCN7 and SNX10 genes (accounting nearly 70% of all cases) using two different integration-free reprogramming methods under feeder-free culture conditions." (PMID 31315669, 2019). "We performed both SeV- and Epi5-mediated inductions from three patients who had disease-associated mutations in three different genes (TCIRG1, SNX10, and CLCN7) representing the diverse genetic heterogeneity of osteopetrosis phenotype and two healthy donors, under the same culture conditions." (PMID 31315669, 2019). "In this paper, a girl affected by osteopetrosis with a novel deletion in SNX10 gene was reported." (PMID 29090071, 2017). "This seemingly contradictory finding is consistent with reports in other osteopetrosis models, and may be due to the very large bone area resulting in a much larger total number of osteoclasts in the Snx10 KD mice (see Discussion)." (PMID 25811986, 2015). "While we suspect that alterations in acidification machinery (e.g., CLC transporters) contribute to the significant loss of resorptive remodeling in osteopetrotic bones, we hypothesized that hyperfusion also contributes to the loss of resorptive function in SNX10- and OSTM1-linked osteopetrosis." (PMID 40964326, 2025). "The role of SNX10 mutations in osteopetrosis has been revealed not long ago." (PMID 29090071, 2017). "HSCT is also used to treat genetic abnormalities in CLCN7, TCIRG1, SNX10, and TNFRSF11A leading to osteopetrosis." (PMID 33350578, 2021). "Patients suffering from this variant of SNX10-based osteopetrosis, as well as from other forms of intermediate disease, nonetheless accumulate debilitating skeletal complications as they age, and may eventually require blood transfusions and curative treatment." (PMID 34095139, 2021). "Mutations leading to an intermediate osteopetrosis form, not as severe as ARO nor as benign as the dominant autosomal form of osteopetrosis, have also been detected in SNX10." (PMID 34095139, 2021). "In contrast, osteoclast-specific knockout of Snx10 resulted in osteopetrosis without rickets or alterations in calcium balance." (PMID 28592808, 2017). "In this study, an affected girl with osteopetrosis was introduced who had no mutation in most common causative genes (TCIRG1, CLCN7 and OSTM1) for the disease, but analysis of SNX10 gene was able to detect a novel homozygous deletion in her." (PMID 29090071, 2017). "Mutations in OSTM1, SNX10, and PLEKHM1 are rare and are also associated with forms of osteopetrosis characterized by the presence of non-functional osteoclasts (osteoclast-rich osteopetrosis)." (PMID 33081155, 2020).
colorectal cancer (12 papers, 2018 to 2025). A primary or metastatic malignant neoplasm that affects the colon or rectum. "For example, sorting nexin 10 (SNX10) deficiency promotes colorectal cancer cell (CRC) proliferation through activation of the CMA pathway, which results in the degradation of the tumor suppressor p21." (PMID 37509689, 2023). "Another mechanism underlining SNX10 mediated colorectal cancer progression was suggested through autophagy." (PMID 36612066, 2022). "Additionally, low expression of SNX10 has been associated with a poor prognosis in patients with stomach adenocarcinoma and colorectal cancer." (PMID 40341994, 2025). "SNX10 deficiency promotes tumor development in colorectal cancer, so altering the downregulated activity of SNX10 may be beneficial in treating colorectal cancer." (PMID 37509689, 2023). "SNX10 deficiency promotes the initiation and progression of colorectal cancer in mice." (PMID 36612066, 2022). "Previous studies indicated that SNX10 exerts tumor-suppressive effects by regulating autophagy through modulating lysosomal degradation pathways via cargo-mediated autophagy in colorectal cancer." (PMID 40810725, 2025). "For example, SNX10 has demonstrated tumor-suppressive effects in colorectal cancer, driving inflammation-related colorectal cancer through a chaperone-mediated autophagy mechanism." (PMID 40341994, 2025). "SNX10 deficiency disrupts the autophagic degradation of proto-oncogene SRC, which in turn activates the STAT3 pathway, thus promoting colorectal cancer initiation and progression." (PMID 36612066, 2022). "Consistent to these observations, SNX10 expression levels were found to be much lower in human colorectal cancer tissues." (PMID 36612066, 2022). "Sorting nexin 10 (SNX10) can suppress the progression of colorectal cancer, liver cancer and stomach cancer." (PMID 34116656, 2021). "In contrast to our findings, SNX10 was reported to have a tumor suppressive effect in mouse inflammation-driven colorectal cancer models, with knockout leading to increased chaperone-mediated autophagy and mTOR activation and reduced autophagic degradation of SRC." (PMID 36795488, 2023). "Therefore, not only has SNX10 been deemed as having tumor suppressor roles in colorectal cancer, it has also been suggested to be a putative marker for hepatocellular cancer with tumor suppressive potential likely regulated by a microRNA." (PMID 36612066, 2022). "SNX10 has been found to play an important role in embryonic development, alcohol-induced liver injury and steatosis, osteoclast formation and resorption activity, colorectal cancer, and phagosome maturation in macrophages." (PMID 33594863, 2021). "Finally, in colorectal cancer cells, Lamp2A expression levels are upregulated as a consequence of the lower protein levels of sorting nexin 10 (SNX10)." (PMID 33643916, 2020). "Moreover, sorting nexin 10 (SNX10) relates to the activation of CMA by regulating expression of p21Cip1/WAF1 and the deficiency of SNX10 induces the tumorigenesis and progression of colorectal cancer via activation of CMA (29355659)." (PMID 33375363, 2020). "In fact, during starvation, normal cells increase the levels of lysosomal LAMP2A by reducing its lysosomal turnover, and in a same way, colorectal cancer cells up-regulate LAMP2A by reducing their degradation through lowering levels of sorting nexin 10 (SNX10)." (PMID 31906065, 2019). "Moreover, FGF14 and SNX10 have demonstrated tumor suppressive properties in colorectal cancer." (PMID 38951817, 2024). "Our recent study also showed that SNX10 KO inhibited macroautophagy, while increased CMA activity, promoting tumorigenesis and progression of colorectal cancer in male mice." (PMID 29867114, 2018).
autosomal recessive osteopetrosis (6 papers, 2015 to 2024). An autosomal recessive form of osteopetrosis caused by mutation(s) in at least 8 genes related to osteoclast function. "Homozygosity for the R51Q mutation in sorting nexin 10 (SNX10) inactivates osteoclasts (OCLs) and induces autosomal recessive osteopetrosis in humans and in mice." (PMID 33975343, 2021). "In 2012, SNX10 mutations were discovered in patients with infantile autosomal recessive osteopetrosis." (PMID 25811986, 2015). "Mutations in sorting nexin 10 (Snx10) have recently been found to account for roughly 4% of all human malignant osteopetrosis, some of them fatal." (PMID 25811986, 2015). "In 2013, nine novel mutations in SNX10 were then described in 14 autosomal recessive osteopetrosis (ARO) patients, and together, SNX10 mutations are now known to accounting for about 4% of known ARO cases, roughly the same proportion as mutations in the RANK-RANKL pathway or in OSTM1." (PMID 25811986, 2015). "SNX10 is one of nine genes (OSTM1, CLCN7, CA2, TNFSF11, TNFRSF11A, PLEKHM1, TCIRG1, and FERMT3) responsible for autosomal recessive osteopetrosis." (PMID 36526684, 2023).
rickets (5 papers, 2015 to 2023). Bone softening and weakening usually caused by deficiency or impaired metabolism of vitamin D. Deficiency of calcium, magnesium, or phosphorus may also cause rickets. "The rickets phenotype of SNX10-KD mice has been linked to dysfunction of gastric epithelial cells, which apparently does not occur in the R51Q SNX10 mice." (PMID 34095139, 2021). "Mutations in SNX10 account for roughly 4% of ARO in humans, often including an osteopetro-rickets phenotype, and Snx10 is required for osteoclast differentiation and function." (PMID 25992615, 2015). "We also observed a mineralization defect in the Snx10 KD mice, consistent with rickets, suggesting that Snx10 is also required for calcium homeostasis." (PMID 25811986, 2015). "Clear indications of rickets were detected in homozygous SNX10 KD mice, in the form decreased bone mineral density and bone mineral content values, presence of non-mineralized osteoid on trabecular surfaces, and metaphyseal fraying and cupping in femurs and tibias." (PMID 34095139, 2021). "Radiograph and micro-CT analysis demonstrated that that the Tcirg1 KO mice were strikingly similar to the Snx10 KD mice by radiograph and micro-CT, with lack of cortical bone, metaphyseal cupping and fraying, and non-mineralized condyles and articulations, all characteristic of rickets." (PMID 25811986, 2015).
atherosclerosis (3 papers, 2023 to 2025). A disease characterized by the build-up of fatty material and calcium deposition in the arterial wall resulting in partial or complete occlusion of the arterial lumen. "SNX10, previously implicated in macrophage-related pathologies such as fatty liver disease and atherosclerosis, was found to be significantly overexpressed in ovarian cancer." (PMID 40426851, 2025). "The rs7780562 variant reduced the expression of the Sorting Nexin 10 (SNX10), a protein associated with diet-induced atherosclerosis, and may reduce CVD risk in our subjects through this pathway." (PMID 38858772, 2024). "For instance, SNX10 deficiency induces macrophage reprogramming via the Lyn-AKT-TFEB signaling axis, attenuating foam cell formation and suppressing atherosclerosis progression." (PMID 40426851, 2025). "SNX10 controls metabolic reprogramming of macrophages in atherosclerosis by enhancing lysosomal biogenesis and lysosomal acid lipase, thus increasing free fatty acids to fuel mitochondrial fatty acid oxidation." (PMID 36795488, 2023). "In cardiovascular diseases, increased SNX10 expression stimulates lipid accumulation in macrophages via the AKT/TFEB signaling pathway, which contributes to atherosclerosis." (PMID 40426851, 2025).
colitis (3 papers, 2016 to 2024). Inflammation of the colon. "To explore the possible role of SNX10 in IBD, we compared the severity of DSS-induced colitis in SNX10−/− and WT mice." (PMID 26856241, 2016). "The number and staining intensity of F4/80-positive cells in colonic tissues of SNX10 KO mice with DSS-induced colitis were significantly lower than those in WT mice with DSS-induced colitis." (PMID 26856241, 2016). "In conclusion, our results demonstrate that SNX10 is a new regulator for macrophage M2 polarization, which is responsible for the protective effects against DSS-induced colitis in SNX10−/− mice." (PMID 26856241, 2016). "Adoptive transfer of SNX10−/− macrophages ameliorated colitis in WT mice." (PMID 26856241, 2016). "By in vivo macrophage depletion and adoptive transfer approach, we further proved that the M2-polarized SNX10−/− macrophages could significantly ameliorated DSS-induced colitis, suggesting that manipulating macrophage polarization targeting SNX10 may be an attractive new strategy for IBD treatment." (PMID 26856241, 2016). "Here, we investigated the effects of sorting nexin 10 (SNX10), a protein involved in endosomal trafficking and osteoclast maturation, on regulation of macrophage polarization and progression of mouse colitis." (PMID 26856241, 2016). "In the present study, we report that SNX10 knockout effectively protected against inflammation and pathological damage in dextran sulfate sodium (DSS)-induced mouse colitis through promoting M2 polarization of macrophages." (PMID 26856241, 2016).
inflammatory bowel disease (3 papers, 2021 to 2023). A spectrum of small and large bowel inflammatory diseases of unknown etiology. "SNX10 presents a crucial role in macrophage polarization and inflammation, and the loss of SNX10 function was proposed to be a potentially promising therapeutic strategy for inflammatory bowel disease." (PMID 35267932, 2022). "Adoptive transfer of helminth protein induced M2 or SNX10 deficiency induced M2 macrophages ameliorated inflammatory bowel diseases in wild-type mice." (PMID 33718268, 2021). "SNX10 contributes to macrophage polarization, with knockdown favoring an antiinflammatory M2 state in inflammatory bowel disease." (PMID 36795488, 2023).